HDAC8 (histone deacetylase 8)
Diseases named in the same sentence as HDAC8 in open-access papers (continued):
Sharing a sentence is not in itself a finding about the gene and the disease.
infection (8 papers, 2011 to 2025). The state of being infected such as from the introduction of a foreign agent such as serum, vaccine, antigenic substance or organism. "Histone deacetylase genes (HDAC1 and HDAC8) had increased expression of L6 alleles, while small nuclear RNA genes (SNORA68 and SNORA72) expressed higher levels of L7 alleles with infection in T cell subsets." (PMID 39880866, 2025). "Molecular analyses revealed comparable infection efficiency, but lower levels of H3K27ac in engram cells overexpressing HDAC8 compared to the control GFP‐expressing cells." (PMID 41178780, 2025). "Similar data were also obtained in HeLa cells, VSV-GFP infection induced the decreased HDAC8 protein." (PMID 39035358, 2024). "In 293T cells, with the increasing infection time and multiplicity of infection, HDAC8 protein expression level decreased gradually." (PMID 39035358, 2024). "In particular, advances in the development of inhibitors of Schistosoma mansoni histone deacetylase 8 have indicated that targeting this enzyme is a promising approach for the treatment of this infection." (PMID 35056137, 2022). "HDAC8 depletion was also found to inhibit infection of Uukuniemi virus (a bunyavirus) suggesting common requirements among late penetrating enveloped viruses." (PMID 22046129, 2011). "In a high-throughput RNAi screen, HDAC8 emerged as one of the proteins required for efficient infection of influenza A X31 strain (A/Aichi/2/68) (H3N2) in A549 cells." (PMID 22046129, 2011). "HDAC8 was found to support infection by promoting LE/LY motility and MT organization at the centrosome, and by increasing centrosome cohesion." (PMID 22046129, 2011). "Interestingly, reduced levels of miRNA-21-3p resulted in increased expression of HDAC8 (histone deacetylase 8), which protects the body from infection by limiting pathogen replication." (PMID 39795977, 2024). "And now, we explored the change of HDAC8 during VSV-GFP infection by Western-blot." (PMID 39035358, 2024). "We found that infection with non-pathogenic E. coli induced HDAC gene expression after 1 h but that the levels were attenuated after 4 d, whereas infection with virulent L. monocytogenes resulted in the delayed but longer-lasting induction of HDACs, particularly HDAC8." (PMID 23035888, 2012). "Thus by dispersing endosomes, nocodazole had an effect on infection and acidification similar to HDAC8 depletion: it reduced the infectivity of endocytosed IAV to half." (PMID 22046129, 2011). "Thus, HDAC8, rootletin and the functionality of centrosomes is critical for the infection of late penetrating viruses." (PMID 22046129, 2011). "Thus, by causing centrosome splitting by an independent mechanism, it was possible to induce a block in infection similar, but not identical, to that caused by HDAC8 depletion." (PMID 22046129, 2011). "That HDAC8 and HDAC1 had opposing effects on centrosome distance and infection was further supported by double transfection experiments where the two were silenced simultaneously." (PMID 22046129, 2011). "It is of interest to note that infection did not correlate with MT anchoring to centrosomes; whereas the split centrosomes in HDAC8-depleted cells were not anchored, the centrosomes in rootletin-depleted cells remained anchored to MT." (PMID 22046129, 2011). "This was confirmed for HDAC1 and HDAC8 by inducing infection without the need for the virus to undergo endocytosis." (PMID 22046129, 2011). "Depletion of HDAC8 and HDAC3 resulted in decreased infection by IAV." (PMID 22046129, 2011). "In addition, Western blot results showed that compared with control cells, in 293T cell line knockout of HDAC8 significantly reduced the protein expression of RIG-I, MAVS, p-TBK1 and p-IRF3 during VSV-GFP infection, which are key regulators of RLRs signaling pathway and subsequent immune response." (PMID 39035358, 2024).
neurodevelopmental disorder (3 papers, 2020 to 2024). A behavioral and cognitive disorder with onset during the developmental period that involves impaired or aberrant development of intellectual, motor, or social functions. "To date, three neurodevelopmental disorders caused by mutations in genes encoding for HDACs (HDAC4, HDAC6 and HDAC8) and thus belonging to the group of chromatinopathies, have been described." (PMID 38753158, 2024). "Four of the identified genes (CUL4B, HDAC8, MED12, and USP9X) have been previously reported to harbor de novo PTVs and Dmis variants in male cases with neurodevelopmental disorders, providing more genetic evidence of their pathogenicity." (PMID 33023636, 2020). "We propose that a multigenic contribution of heterozygous variants in HDAC8 and the FA/BRCA pathway might have a role in the phenotype of this neurodevelopmental disorder." (PMID 35052418, 2021).
) malformation syndrome (2 papers, 2018 to 2022). "The best characterized cohesinopathy is CdLS, an autosomal dominant (NIPBL, SMC3, and RAD21) or X-linked (SMC1A and HDAC8) malformation syndrome." (PMID 36467423, 2022). "CdLS, an autosomal dominant (NIPBL, SMC3, and RAD21) or X-linked (SMC1 and HDAC8) malformation syndrome, represents the best characterized cohesinopathy." (PMID 36467423, 2022).
Hematological Malignancies (2 papers, 2020 to 2024). "Together, we provide the evidence for the role of HDAC8 in hematopoietic stem cell differentiation in zebrafish and AML cell lines, suggesting HDAC8 inhibition as a therapeutic target in hematological malignancies." (PMID 33015043, 2020).
neurological diseases (2 papers, 2022 to 2024). "Elucidating the physiological functions of HDAC8 would help to understand mechanisms in neurological diseases and develop pharmacological interventions." (PMID 38473789, 2024). "The reported studies thus served as a proof-of-concept that HDAC8 inhibition might offer novel therapeutic options for neurological disorders." (PMID 36077415, 2022).
HDAC8 also shares sentences with these, for which no sentence is quoted: chronic atrial and intestinal dysrhythmia (4 papers); Warsaw breakage syndrome (3); cardiovascular disease (2); depression (2); gastroesophageal reflux (2); idiopathic pulmonary fibrosis (2); myopathy (2); renal cell carcinoma (2); rheumatoid arthritis (2); Roberts-SC phocomelia syndrome (2); uroepithelial carcinoma (2); adenocarcinoma (1); adenoid cystic carcinoma (1); adenoma (1); alcoholic hepatitis (1); Alpha-thalassemia (1); Aortic dissection (1); aristolochic acid nephropathy (1); atherosclerosis (1); autism spectrum disorder (1); B-cell lymphomas (1); Brachycephaly (1); brachydactyly mental retardation syndrome (1); Burkitt lymphoma (1); CHOPS syndrome (1); cleft palate (1); Cognitive impairment (1); colorectal adenocarcinoma (1); congenital hypothyroidism (1); COVID-19 (1).
A further 40 diseases each share a sentence with HDAC8 in 1 paper.